DCLK1 (doublecortin like kinase 1)
Diseases named in the same sentence as DCLK1 in open-access papers (continued):
Sharing a sentence is not in itself a finding about the gene and the disease.
cancer (continued). "In our long-term in vivo efficacy study, we demonstrated that licofelone and gefitinib can target COX-2, 5-LOX, EGFR, and cancer stem cell marker DclK1, and can potently inhibit PanIN progression to PDAC without any side effects." (PMID 26429877, 2015). "Despite these compelling findings, the effect of inhibiting DCLK1 kinase activity has not been investigated in cancer." (PMID 24885928, 2014). "Although siRNA-mediated knockdown of DCLK1 gene expression is antiproliferative and induces tumor growth arrest, the effect of inhibiting DCLK1 kinase activity in cancer had not been previously assessed." (PMID 24885928, 2014). "Besides inhibition of cholesterol biosynthesis, FLV disrupts DCLK1-microtubule axis, which adversely affects HCV replication and cancer cell survival." (PMID 24260365, 2013). "Although its full substrate repertoire remains poorly defined—with only a handful of direct targets validated—DCLK1 modulates phosphorylation events that influence β-catenin, JNK, and downstream effectors in the MAPK and PI3K–AKT pathways, suggesting a broad role in cancer and tissue homeostasis." (PMID 40563698, 2025). "In another study, they targeted DCLK1 as a critical oncogenic regulatory factor using nanoparticle (NP) technology to deliver DCLK1-specific small interfering RNA (siRNA) in HCT116 xenografts aimed to upregulate tumor suppressor microRNAs (let-7a, miR-200a, and miR-144) for cancer therapy in CRC." (PMID 35717205, 2022). "In addition, DCLK1 was found to be highly expressed in several malignancies and to be involved in the regulation of tumorigenesis, tumor stemness and epithelial-mesenchymal transition (EMT) in cancer, including pancreatic, colorectal and liver cancer." (PMID 33762936, 2021). "Indeed, the ablation of Dclk1+ tuft cells and blockade of NGF/Trk signaling inhibit epithelial regeneration and tumorigenesis in an M3R-dependent manner, highlighting the importance of tuft cells as a component of the cancer niche." (PMID 31405140, 2019). "However, high DCLK1 expression was only notably correlated with positive lymph node metastasis and poorly differentiated cancer in Asian region but not in non-Asia region." (PMID 29246000, 2017). "IBC-NED with low DCLK1 expression showed the lowest DFS rate, when compared to non-NED luminal cancers regardless of the neuroendocrine expression pattern (DCLK1 low/ neuroendocrine focal: log-rank=8.861, p = 0.003; DCLK1 low/ neuroendocrine diffuse: log-rank=7.211, p = 0.007)." (PMID 26621833, 2016). "Additionally, the results of our study suggest the possibility that DCLK1 kinase activity may be involved in regulating proliferation, cell cycle, EMT, and stemness pathways in cancer." (PMID 24885928, 2014). "The role of DCLK1 in the regulation of pluripotency in a cancer context is novel and may present an exciting new target for anti-cancer based therapy." (PMID 24040120, 2013). "Despite these similarities and DCLK1′s emerging role as a TSC in gastrointestinal cancers, it has not been assessed in cancers of the excretory system." (PMID 25605241, 2015). "Therefore, the development of novel therapeutics that target DCLK1 may reduce CSCs and EMT, which may be a promising treatment strategy for the eradication of cancer without recurrence." (PMID 27335684, 2016).
tumor (153 papers, 2007 to 2026). "DCLK1 is strongly linked to the infiltration of multiple immune cell types, especially tumour-associated macrophages (TAMs) and regulatory T-cells (Treg)." (PMID 38062554, 2024). "Recognized as a hallmark of tumor stemness, DCLK1 plays a pivotal role in tumorigenesis, and DCLK1 isoforms, shaped by alternative promoter usage and splicing, can reveal potential therapeutic touchpoints." (PMID 38003596, 2023). "DCLK1 is a microtubule-associated kinase that regulates tumour growth and progression and is an antigen of tumour stem cells of colorectal cancer." (PMID 36428480, 2022). "Our previous investigations, in line with others, also indicated the significant association between higher expression of DCLK1 and aggressive nature of the tumor, advanced stages, and higher tumor grade on both protein and mRNA levels in CRC patients." (PMID 35717205, 2022). "Cytoplasmic expression of DCLK1-S, a novel DCLK1 isoform, has been shown to be associated with tumor aggressiveness and worse disease-specific survival in CRC." (PMID 36551919, 2022). "DCLK1 expression is associated with the expression of immune cell markers for Treg, markers of monocytes, tumor-associated macrophages (TAMs), and M2 macrophages that suppresses the CD8+ T cells functionality, leading to immune cell function loss." (PMID 36250024, 2022). "In this study, we observed EMT associated gene expression signature enriched in Dclk1+ tumor cells in both mouse and human PDACs." (PMID 33393460, 2021). "Gastrointestinal work focused on DCLK1 has tightly linked it to immune response and to immune infiltrates in the tumor." (PMID 34830884, 2021). "DCLK1 inhibitors may reduce the risk of radiation-induced neoplasia by limiting the regeneration of damaged progenitor cells." (PMID 40563698, 2025). "Furthermore, DCLK1 expression has been associated with the recruitment and activation of regulatory T cells (Tregs) and MDSCs, which together dampen anti-tumor immunity and facilitate tumor immune evasion." (PMID 40563698, 2025). "Additionally, DCLK1 is recognised as a regulator of type II immune response and linked with functional regulation of the tumour microenvironment." (PMID 38062554, 2024). "DCLK1-expressing cells in the intestinal epithelium play a crucial role in DNA damage response and cell survival after radiation-induced injury, and are implicated in decreasing radiosensitivity and sustaining tumor progression." (PMID 37686516, 2023). "DCLK1 is recognized as a possible marker since it is over-expressed in a variety of solid malignant tumors and has been associated to malignant biological activity and poor tumor prognosis." (PMID 36704202, 2022). "During human neoplasia, hypermethylation of DCLK1-L appears to cause a predominant switch to the short isoform, which confers a more invasive tumor phenotype suggesting that DCLK1 isoforms likely have distinct functions." (PMID 34226497, 2021). "It is plausible that a subset of patients in which NOTCH acts as an oncogene may also display overexpressed DCLK1, allowing the tumor to co-opt and amplify mechanisms underlying HNSCC initiation and progression." (PMID 34336664, 2021). "DCLK1 expression potentially contributes to regulation of tumor-associated macrophages (TAMs) and Treg, and may thereby increase CD8+ T cell inhibition and induce T cell exhaustion." (PMID 31979136, 2020). "Notably, DCLK1 variants containing the extracellular domain show restricted expression in normal tissue but overexpression in tumor tissue." (PMID 33348546, 2020). "Dclk1 is a microtubule-associated serine-threonine protein kinase involved in tumor stemness and progression, by promoting survival signaling, migration and tumor cell pluripotency, mainly through an intensive crosstalk with miRNAs." (PMID 35582268, 2019).
tumor (continued). "Interestingly, intestinal Dclk1-positive tuft cells have been proposed to be long-lived, and indeed inflammation in conjunction with an oncogenic mutation specific to Dclk1-positive tuft cells caused tumor formation in a mouse model of colorectal cancer." (PMID 33627749, 2021). "Therefore, it is tempting to speculate that DCLK1 or the DCLK1+ cell may regulate polarization of tumor-associated macrophages (TAMs)." (PMID 31979136, 2020). "DCLK1 expression correlated strongly with established markers of stem-like, metastasis-initiating tumor cells across the patient-derived ascites cultures." (PMID 42210222, 2026). "Mechanistically, DCLK1 promoted early metastatic colonization by enhancing tumor cell adhesion, mesothelial clearance, and mesothelial-to-mesenchymal transition." (PMID 42210222, 2026). "In colorectal and pancreatic cancers, DCLK1 overexpression suppresses tumor-suppressive miR-143/145, indirectly enhancing KRAS expression and downstream ERK/MAPK activity." (PMID 40563698, 2025). "Herein, the sphere formation assays revealed that upregulating DCLK1 increased but downregulating DCLK1 decreased the size and number of tumor spheroids formed from 22Rv1 and PC3 cells." (PMID 39781521, 2025). "After a 16-day treatment via gavage administration (25 mg/kg, every other day), we observed a significant reduction in tumor size, tumor weight, and growth rate in the DCLK1-IN-1 group." (PMID 40775208, 2025). "The results of in vitro experiments showed that verteporfin treatment significantly reduced the colony size and number of DCLK1-overexpressing 22Rv1 cells, and a similar abolishing effect was observed in the tumor sphere formation assay." (PMID 39781521, 2025). "Collectively, these pathways position DCLK1-positive tuft cells and CSCs as central mediators of post-irradiation regeneration and tumor radioresistance, establishing DCLK1 as both a key regulator of epithelial recovery and a potential oncogenic driver." (PMID 40563698, 2025). "As a result, the exploration into dual-targeted drug delivery systems that incorporate more tumor-specific markers, such as DCLK1, to enhance selectivity and therapeutic precision, is a promising strategy for the future of drug development against BCSCs." (PMID 40869256, 2025). "Preclinical studies show that DCLK1 blockade (via small molecules or siRNA) impairs DNA repair in CSCs, enabling tumor control at lower radiation doses." (PMID 40563698, 2025). "Overall, DCLK1 inhibition offers significant therapeutic promise for enhancing tumor radiosensitivity, reducing recurrence, and minimizing radiation-induced GI injury." (PMID 40563698, 2025). "Research supports the notion that the overexpression of DCLK1 in tumor cells will likely contribute to stemness and self-renewal." (PMID 40869256, 2025). "Increasing evidence supports the important role of DCLK1 in regulating tumor immunity, making it a promising target for therapeutic approaches against solid tumors." (PMID 38892399, 2024). "In mice, tuft cell depletion in the Apcflox/+ intestinal tumorigenesis model results in a decreased tumor burden, while succinate administration restores DCLK1+ tuft cells and increases tumor burden." (PMID 37863104, 2024). "Unlike Lgr5, which is shared by normal and tumor stem cells, DCLK1 was shown to be able to distinguish between normal and tumor stem cells in the gut." (PMID 38254219, 2024). "DCLK1 has been reported to influence tumor stemness, EMT, and metastasis in several solid tumors, and has been linked to pro-inflammatory NF-κB signaling activation by interacting with IKKβ." (PMID 38928187, 2024). "For the underlying mechanism, we proposed that the PI3K/AKT/mTOR pathway is the key process for the role of DCLK1 in tumor progression and the occurrence of the EMT program." (PMID 38980538, 2024).
tumor (continued). "For example, DCLK1 knockdown in colorectal cancer cells results in the upregulation of tumor suppressor miRNAs such as miR-143 and miR-145, leading to reduced cell proliferation and migration." (PMID 38928187, 2024). "Recently, the role of DCLK1 in fostering immune suppression within the tumor microenvironment has garnered increasing attention." (PMID 38980538, 2024). "Our results revealed that the overexpression of DCLK1 supported tumor proliferation and clonal formation, and promoted the migration and invasion capabilities of CCA cells." (PMID 38980538, 2024). "We established DCLK1 knockout and DCLK1 overexpression cell lines for Colony Formation Assay and Transwell experiments to explore the tumor-promoting role of DCLK1." (PMID 38980538, 2024). "In the ApcMin model, pedigree tracing of Cre/lox revealed that cells expressing DCLK1 in intestinal adenoma were responsible for continuous production of tumor cells." (PMID 39839479, 2024). "Doublecortin-like kinase 1 (DCLK1), a serine–threonine protein kinase, is a marker of tumor stemness in many solid tumor cancers, including HCC." (PMID 38928187, 2024). "Another antigen implicated in tumor growth and regulation of EMT in CRC is doublecortin-like kinase 1 (DCLK1)." (PMID 37175871, 2023). "The results demonstrated that the effects of DCLK1 knockout on tumor growth mainly depend upon anti-tumor immune response." (PMID 37069669, 2023). "The tumor growth curves showed that DCLK1-IN-1 and S31-201 significantly inhibited the tumor growth when compared to the solvent group, especially DCLK1-IN-1." (PMID 37069669, 2023). "Several studies have also revealed that DCLK1 is highly expressed in multiple tumors and is recognized as a putative marker in certain tumor stem cells." (PMID 37239162, 2023). "As a newly identified gastrointestinal tumor stem cell marker, DCLK1-related functions in tumor malignant progression have been gradually revealed in the past decade." (PMID 37069669, 2023). "To investigate the effect of DCLK1-IN-1 on antitumor immunity, we conducted in vivo experiments using 4T1 subcutaneous tumor model." (PMID 37069669, 2023). "Here, we firstly explored the impacts of DCLK1 on tumor cells as well as their immune microenvironment in TNBC and potential therapeutic strategies for TNBC patients with high DCLK1 expression." (PMID 37069669, 2023). "Tumor stem cell marker DCLK1 is essential for maintaining tumor cell stemness via the Wnt/β-Catenin pathway and facilitates the development of EGFR-TKIs resistance." (PMID 37089959, 2023). "A growing body of evidence suggests that DCLK1 is a marker for CSCs and a promising target for therapies aiming to halt tumor recurrence and metastasis." (PMID 38003596, 2023). "Knockdown studies and DCLK1 kinase inhibitor studies have shown improvements in reducing tumorigenesis and modulating the tumor microenvironment." (PMID 38003596, 2023). "Evidence suggests that DCLK1 plays a crucial role in tumor development beyond its essential function in the nervous system." (PMID 37239162, 2023). "A recent study showed the use of Doublecortin-like kinase 1 (DCLK1)-based CAR-T cells as a treatment strategy for eradicating CRC tumor stem cells." (PMID 37420216, 2023). "Anti-CD8 treatment significantly abrogated the anti-tumor effects of DCLK1 knockout, suggesting antitumor immunity of DCLK1 knockout relied on CD8+ T cells." (PMID 37069669, 2023). "The increased tumor DCLK1 expression was significant in 56Fe relative to γ-rays (p = 0.012) or to spontaneous (p < 0.001) tumors." (PMID 37686516, 2023). "It has been shown that doublecortin-like kinase 1 (DCLK1) plays an important role during pancreatic tumorigenesis by negatively regulating a set of miRs with a tumor-suppressing function such as miR-145, miR-200a, b, c, and let-7." (PMID 37239940, 2023). "sEV miR-7 inhibits PC cell proliferation and induces apoptosis by directly targeting MAP3K9, and miR-195 mediate tumor-suppressive effects in PC by targeting DCLK1." (PMID 34980146, 2022).
tumor (continued). "Both in vitro and in vivo evidence have emphasized the potential oncogenic functions of DCLK1 in tumor initiation, self-renewal ability, tumor invasion, epithelial-mesenchymal transition (EMT), and metastasis." (PMID 35717205, 2022). "Preclinical and in vitro evidence have suggested the potential oncogenic roles of DCLK1 in tumorigenesis, tumor maintenance, invasion, migration, apoptosis, metastasis, and drug resistance in CRC." (PMID 35717205, 2022). "Double cortin-like kinase 1 (DCLK1), a microtubule-associated protein, maintains stemness in CRC cells, and it is a putative tumor stem cell (TSC) marker in CRC mouse models." (PMID 36458008, 2022). "Especially, the relationship between DCLK1, chemoresistance and tumour stem cells needs to be further clarified." (PMID 35522902, 2022). "In total, five studies comprising 673 patients revealed a connection between DCLK1 expression and tumor size." (PMID 35717205, 2022). "Isoform-specific functions of DCLK1 have shed new light on different functions of DCLK1 short (DCLK1-S) and DCLK1 long (DCLK1-L) isoforms in tumor initiation, growth, and metastasis." (PMID 35717205, 2022). "The elevated levels of DCLK1 were closely correlated with poorer outcomes and tumour recurrence and metastasis." (PMID 35522902, 2022). "Consistent with the deceleration of tumor growth, a significant reduction in tumor-repopulating potential was observed upon DCLK1-IN-1 treatment." (PMID 35910805, 2022). "IL-25 promotes tumorigenesis through maintaining tumour stemness, and genetic IL-25-deficiency led to reduced expression of stem cell markers Lgr5, CD133 and DCLK1." (PMID 36263033, 2022). "And elevated levels of DCLK1 were closely correlated with poorer outcomes and higher rates of tumour recurrence and metastasis." (PMID 35522902, 2022). "Another recent study in PDAC cell lines demonstrated a correlation between DCLK1 expression and expression of key tumor immune checkpoint ligand PD-L1." (PMID 34830884, 2021). "Given that DCLK1 expressing cells play a significant role in tumor generation, the targeting of this protein by HNK would be a significant mechanism for suppressing tumorigenesis." (PMID 34206989, 2021). "First, we revealed that Dclk1+ PanIN and PDAC cells supplied descendant cells in established PanIN and PDAC within native environments in vivo, demonstrating the stem cell activity of Dclk1+ tumor cells within primary pancreatic malignancy." (PMID 33393460, 2021). "DCLK1 is highly expressed in several malignancies and is a marker of tumor stem cells that plays a critical role in the self-renewal capacity of cells derived from these tumors." (PMID 33762936, 2021). "Along with oncogenes, DCLK1 also modulates stem cell pluripotency in PDAC through the regulation of multiple tumor suppressor microRNAs (miRNAs/miRs) such as miR-200, miR-145 (miR143/145 cluster), and let-7a and their downstream pro-tumorigenic pathways." (PMID 34453639, 2021). "Although the results presented here are promising, they are exploratory in nature, and a more faithful representation of the tumor-immune interactions in RCC is necessary to further untangle this property of DCLK1-IN-1." (PMID 34830884, 2021). "To investigate the status of DCLK1 in regard to the RCC tumor microenvironment, we assessed its correlation with immune infiltrates in TCGA’s KIRC dataset using TIMER." (PMID 34830884, 2021). "Doublecortin-like kinase 1 (DCLK1) is an understudied bi-functional kinase with a proven role in tumour growth and development." (PMID 34545159, 2021). "Their structural study reveals insights into the mode of action of the inhibitor DCLK1-IN-1 and sets the basis for the design of isoform-specific inhibitors of DCLK1, which plays a role in tumour growth and development." (PMID 34545159, 2021).